IKBKE (inhibitor of nuclear factor kappa B kinase subunit epsilon)
Diseases named in the same sentence as IKBKE in open-access papers (continued):
Sharing a sentence is not in itself a finding about the gene and the disease.
autoimmune disease (4 papers, 2015 to 2025). A disorder resulting from loss of function or tissue destruction of an organ or multiple organs, arising from humoral or cellular immune responses of the individual to their own tissue constituents. "In addition to the IKBKE gene, the WFS1 gene has been identified as a gene associated with “autoimmune diseases,” as defined by The Human Gene Mutation Database." (PMID 39524436, 2024).
lung cancer (4 papers, 2020 to 2025). A malignant neoplasm involving the lung. "Meanwhile, overexpression of IKBKE induced by STAT increased chemoresistance in NSCLC (non‐small cell lung cancer) cells." (PMID 31733040, 2020). "Guo et al54 examined the expression of IKBKE in 98 NSCLC (non‐small cell lung cancer) samples and demonstrated that 54 tumor samples had elevated IKBKE expression by immunohistochemistry." (PMID 31733040, 2020).
systemic lupus erythematosus (4 papers, 2015 to 2024). An autoimmune multi-organ disease typically associated with vasculopathy and autoantibody production. "The upstream single nucleotide polymorphism of IKBKE (rs2297550-G) is a genome-wide association study risk variant of systemic lupus erythematosus, and is associated with decreased IKBKE expression in T cells by expression quantitative trait locus analysis." (PMID 39524436, 2024). "The IKBKE has been proven to be associated with systemic lupus erythematosus (SLE) in a genome-wide association study (GWAS) conducted by our group." (PMID 32146614, 2020).
type 2 diabetes (4 papers, 2020 to 2024). "IKBKE inhibitors have been developed and used in clinical trials to treat patients with Type 2 diabetes." (PMID 32324216, 2020). "We propose that IKBKE inhibitors, such as Amlexanox which has been used in clinical trials for Type 2 diabetes, may be repurposed to provide therapeutic advantage for advanced PC patients." (PMID 32324216, 2020).
Alzheimer disease (3 papers, 2020 to 2024). A progressive, neurodegenerative disease characterized by loss of function and death of nerve cells in several areas of the brain leading to loss of cognitive function such as memory and language. "In RT-PCR assays, pre-treatment with GLE decreased mRNA expression of CHUK, NFκB1/p150, and IKBKE (NFƙB signaling), which may be associated with the neuropathology of Alzheimer’s disease." (PMID 32480240, 2020).
colorectal cancer (3 papers, 2020 to 2021). A primary or metastatic malignant neoplasm that affects the colon or rectum. "Chen et al43 showed that IKBKE knockdown could inhibit the proliferative capacity of colorectal cancer cell lines." (PMID 31733040, 2020). "Chen et al43 testified that IKBKE physically interacted with β‐catenin by co‐IP (co‐immunoprecipitation) and that IKBKE phosphorylated β‐catenin, probably at Ser680 and Ser681, to restrain its hyperactivation, thereby promoting colorectal cancer (CRC) cell proliferation." (PMID 31733040, 2020). "Göktuna et al42 found that IKBKE promoted intestinal cell survival and established an inflammatory tumor microenvironment in CRC (colorectal cancer) upon constitutive Wnt activation." (PMID 31733040, 2020).
lymphoma (3 papers, 2016 to 2020). A malignant (clonal) proliferation of B- lymphocytes or T- lymphocytes which involves the lymph nodes, bone marrow and/or extranodal sites. "Recently, Zhang et al58 demonstrated that IKBKE played an important role in maintaining the activity of STAT3 in lymphoma cell lines, thereby accelerating lymphoma growth and malignant progression." (PMID 31733040, 2020).
myelofibrosis (3 papers, 2021 to 2024). A partial or complete replacement of the bone marrow stroma by fibrous tissue. "On the other hand, Momelotinib, a recently approved multi-kinase inhibitor for the treatment of myelofibrosis and anemia, was used in this study at a concentration targeting IKBKE, a TBK1 paralogue." (PMID 38724853, 2024). "CYT387 (momelotinib), a JAK1/2 kinase inhibitor tested in clinical trials for myelofibrosis, has recently been identified as a potent IKBKE inhibitor." (PMID 34544426, 2021).
panic disorder (3 papers, 2015 to 2024). An anxiety disorder characterized by multiple unexpected panic attacks with persistent concern of recurring attacks. "Another gene on chromosome 1, IKBKE (inhibitor of kappa light polypeptide gene enhancer in B-cells, kinase epsilon) was studied with 210 panic disorder patients, 356 healthy controls." (PMID 31435520, 2018). "In order to investigate the possible role of IKBKE gene in major depressive disorder (MDD) and panic disorder (PD), we conducted a case–control genetic association study concerning these disorders." (PMID 25798331, 2015). "A case-control genetic association study involving the IKBKE gene, which encodes the IKKε protein involved in innate immunity and proinflammatory responses, revealed significant associations between IKBKE single-nucleotide polymorphism and MDD, as well as suggestive associations with panic disorder." (PMID 38888950, 2024).
prostate adenocarcinoma (3 papers, 2020 to 2026). "Specifically, IKBKE was significantly downregulated in prostate adenocarcinoma (PRAD) samples relative to normal prostate tissues." (PMID 41542764, 2026). "Indeed, upon investigation of all prostate data sets, it appears that IKBKE is amplified in CRPC (27.14%; 19/70 cases) compared to prostate adenocarcinoma (1.74%; 82/4712 cases) and normal prostate (0%; 0/313 cases)." (PMID 32324216, 2020).
breast invasive carcinoma (2 papers, 2024 to 2025). "Transfection of CA1a cells with an IKBKE siRNA pool resulted in a phenotypic reversion from invasive breast cancer to DCIS and decreased cell proliferation." (PMID 40468448, 2025). "Specifically, DDX58, C6orf150, IKBKE, TBK1, and IRF3 exhibited a pronounced increase in breast invasive carcinoma (BRCA), while MAVS and TMEM173 expression was significantly lower in BRCA compared to normal controls." (PMID 38817870, 2024). "We used a commercially available peptide array in combination with siRNA-based functional validation and identified the kinases IKBKE and MAPK8 as mechano-regulated proteins critical for the matrix stiffness-induced phenotypic switch from DCIS to invasive breast cancer." (PMID 40468448, 2025).
colon cancer (2 papers, 2019 to 2020). "Thus, IKBKE expression was considered to be associated with the resistance of colon cancer cells to VCR." (PMID 31733040, 2020). "In a study of drug resistance, Zhao et al44 observed that IKBKE was highly expressed in VCR (vincristine)‐resistant colon cancer cells." (PMID 31733040, 2020). "Among the upstream regulators (TFs, kinases, and MMTRs) of the DEGs, the expression of STAT3, RPS6KA5, IKBKE, ERBB2, MTOR, and NFKB1 had a positive correlation with OS in colon cancer, while the expression of CDK1, CDK5, and BRD2 had a negative correlation with OS in colon cancer." (PMID 31186640, 2019).
hepatocellular carcinoma (2 papers, 2020 to 2024). A malignant tumor that arises from hepatocytes. "Tang et al37 demonstrated that miR‐4458 targeted IKBKE to reduce its expression in human hepatocellular carcinoma to suppress cancer cell growth." (PMID 31733040, 2020).
malignant glioma (2 papers, 2017 to 2020). A grade III or grade IV glioma arising from the central nervous system. "We first investigated IKBKE expression levels in normal brain tissue, a low-grade malignant glioma cell line (H4) and high-grade malignant glioma cell lines (U87-MG, LN229, U251, LN308, A172 and SnB19) using real-time RT-PCR and western blotting." (PMID 28548934, 2017). "So we assumed that IKBKE promoted malignant glioma growth and EMT via enhancing the expression of YAP1 and TEAD2." (PMID 28548934, 2017). "Altogether, these findings showed that knockdown of IKBKE inhibited the tumourigenesis of malignant glioma in vivo." (PMID 28548934, 2017). "Collectively, our results suggest that IKBKE plays a pivotal role in regulating cell proliferation, invasion and epithelial–mesenchymal transition of malignant glioma cells in vitro and in vivo by impacting on the Hippo pathway." (PMID 28548934, 2017). "Our findings also serve as a reminder that IKBKE may be a potential new target for the treatment of malignant glioma." (PMID 28548934, 2017). "Then, we verified that knockdown of IKBKE inhibits tumourigenesis in vivo by creating nude mouse subcutaneous and intracranial models, thus illustrating that IKBKE, as an oncoprotein, played a crucial role in malignant glioma progression." (PMID 28548934, 2017). "Therefore, targeting IKBKE may become a new strategy to treat malignant glioma." (PMID 28548934, 2017).
psoriasis (2 papers, 2015 to 2017). An autoimmune condition characterized by red, well-delineated plaques with silvery scales that are usually on the extensor surfaces and scalp. "Recently, the largest meta-analysis of GWAS for psoriasis has identified 16 novel genetic loci for psoriasis, including CHUK on chromosome 10q24.31, FASLG on chromosome 1q24.3 and IKBKE on chromosome 1q32.1, which are associated with the NF-κB signaling pathway." (PMID 29232931, 2017).
renal clear cell carcinoma (2 papers, 2020 to 2025). "Ghatalia et al48 reported that the expression of IKBKE was much higher in metastatic renal clear cell carcinoma tissues than in primary tumors using kinase gene expression profiling analysis." (PMID 31733040, 2020). "In addition, IKBKE overexpression in metastases was also identified by TCGA (The Cancer Genome Atlas) analysis, which indicated that IKBKE may play a role in the metastasis of renal clear cell carcinoma." (PMID 31733040, 2020).
anxiety disorder (1 paper, 2015). A category of psychiatric disorders which are characterized by anxious feelings or fear often accompanied by physical symptoms associated with anxiety. "The results of this study confirm our initial findings and indicate a possible role of IKBKE gene in mood and anxiety disorders." (PMID 25798331, 2015). "The presented results confirm our initial findings and indicate a possible role of IKBKE gene in mood and anxiety disorders." (PMID 25798331, 2015).
brain tumor (1 paper, 2017). "IHC showed that the expression levels of IKBKE was significantly lower in the brain tumor tissue of amlexanox-treated mice." (PMID 29048430, 2017). "The data demonstrated that amlexanox not only significantly reduced brain tumor growth and the expression of IKBKE but also prolonged the survival of the intracranial models, suggesting a good BBB permeability of amlexanox." (PMID 29048430, 2017).
cholangiocarcinoma (1 paper, 2024). A carcinoma that arises from the intrahepatic biliary tree (intrahepatic cholangiocarcinoma) or from the junction, or adjacent to the junction, of the right and left hepatic ducts (hilar cholangiocarcinoma). "The results indicate a significant upregulation of IKKε (encoding gene IKBKE) and TBK1 expression but a decrease in IRF3 expression within the intrahepatic cholangiocarcinoma metastasis group." (PMID 38817870, 2024). "To gain a deeper understanding of the relevance and underlying mechanisms of the innate immune pathway in cholangiocarcinoma, we investigated the expression levels of DDX58, MAVS, C6orf150, TMEM173, IKBKE, TBK1, and IRF3 in different cell types using the TISCH2 database." (PMID 38817870, 2024). "And we observed significant positive correlations between the expression levels of DDX58, C6orf150, TMEM173, IKBKE, and TBK1, and the infiltration levels of macrophages in cholangiocarcinoma." (PMID 38817870, 2024). "Tissue samples from the HPA database were analyzed to determine the functions of DDX58, MAVS, C6orf150, TMEM173, IKBKE, TBK1, and IRF3 in cholangiocarcinoma cells." (PMID 38817870, 2024).
endometrial cancer (1 paper, 2025). Primary or metastatic malignant neoplasm involving the endometrium (mucous membrane that lines the endometrial cavity). "This study provides new insights into IKBKE as a potential molecular target that contributes to understanding the mechanisms underlying progestin resistance in endometrial cancer." (PMID 41378297, 2025). "The regulatory effect of IKBKE on endometrial cancer cell invasion requires subsequent experimental validation." (PMID 41378297, 2025).
gastritis (1 paper, 2016). Inflammation of the stomach. "The rate of IKBKE, NF-κB p65 and phospho-NF-κB p65 positivity in gastritis tissues were just 19.3%, 0% and 4%, respectively." (PMID 26934326, 2016).
intestinal cancer (1 paper, 2020). "In addition, Göktuna et al42 discovered that IKBKE established a proinflammatory signature in the intestine upon constitutive Wnt signaling and that genetic ablation of IKBKE in β‐catenin‐driven models of intestinal cancer‐reduced tumor incidence and consequently extended survival." (PMID 31733040, 2020).
Kaposi's sarcoma (1 paper, 2020). A malignant neoplasm characterized by a vascular proliferation which usually contains blunt endothelial cells. "They found that IKBKE was critically required for tumorigenesis by activating the NF‐κB pathway and that IKBKE expression was drastically upregulated in Kaposi sarcoma‐like lesions and that loss of IKBKE abolished tumor formation." (PMID 31733040, 2020). "Recently, Wang et al59 certified that IKBKE promotes NF‐κB subunit RelA (also known as p65) phosphorylation at serine 468, which correlated with NF‐κB activation and inflammatory cytokine expression in Kaposi sarcoma." (PMID 31733040, 2020).
liver cancer (1 paper, 2024). An epithelial or non-epithelial malignant neoplasm that arises from the liver. "The expression of HSPA1A and IKBKE was significantly elevated in liver cancer tissues, consistent with our previous findings." (PMID 39000042, 2024).
mood disorder (1 paper, 2024). A cognitive disorder a disturbance in which the person's mood is hypothesized to be the main underlying feature. "The proinflammatory properties of the IKBKE gene and its involvement in innate immunity could provide a mechanistic link between the immune responses in vitiligo and the increased susceptibility to mood disorders such as MDD." (PMID 38888950, 2024).
oral cancers (1 paper, 2020). "Recently, Li et al89 reviewed that targeting IKBKE with three TBK1/IKBKE dual inhibitors, including WO2009032861, SAR and Domainex, could powerfully inhibit cell viability and tumor development in human breast, prostate, and oral cancers both in vivo and in vitro." (PMID 31733040, 2020).
osteoporosis (1 paper, 2024). A condition of reduced bone mass, with decreased cortical thickness and a decrease in the number and size of the trabeculae of cancellous bone (but normal chemical composition), resulting in increased fracture incidence. "Interestingly, analysis of hBMSCs revealed elevated IKBKE expression in cells derived from osteoporosis patients." (PMID 39430247, 2024).
polyarthritis (1 paper, 2024). "Herein a woman with a novel functional variant in IKBKE, who had been experiencing polyarthritis and remittent fever for 20 years, is described." (PMID 39524436, 2024).
prostate tumors (1 paper, 2026). "As treatment of IKBKE-e ASOs largely enhanced the IR-induced innate immune response in cultured cells, we next sought to determine whether IKBKE-e ASO in combination with IR induces an innate immunity response in mice that could be harnessed to overcome ICI resistance in murine prostate tumors." (PMID 41542764, 2026).
renal carcinoma (1 paper, 2024). A carcinoma arising from the epithelium of the renal parenchyma or the renal pelvis. "We also assessed IKBKE protein expression in various cell lines, including a renal tubular epithelial cell line (HK-2) and renal cancer cell lines (Caki-1, 769-P and 786-O)." (PMID 39664571, 2024). "The CCK-8 assay, EDU assay, and Annexin V/7AAD staining assay revealed that silencing IKBKE increased sunitinib sensitivity in renal cancer cells, while overexpression of IKBKE decreased the sensitivity of renal cancer cells to sunitinib." (PMID 39664571, 2024). "Taken together, these data demonstrate that IKBKE can regulate the sensitivity of renal cancer cells to sunitinib, and such regulation is primarily through the IKBKE-RRM2 axis." (PMID 39664571, 2024). "Intriguingly, we found that IKBKE silencing effectively suppressed renal cancer cell growth and stimulated cell apoptosis." (PMID 39664571, 2024). "Cell cycle analysis revealed that the depletion of IKBKE led to significant G2/M phase arrest in renal cancer cells." (PMID 39664571, 2024). "The CCK-8 assay demonstrated that IKBKE silencing significantly inhibited renal cancer cell growth." (PMID 39664571, 2024). "Furthermore, we found that RRM2 depletion mitigated the alterations in the IC50 values of sunitinib induced by either the overexpression or knockdown of IKBKE in renal cancer cells." (PMID 39664571, 2024). "Furthermore, Annexin V/7AAD staining and flow cytometry analysis indicated that IKBKE silencing promoted apoptosis in renal cancer cells." (PMID 39664571, 2024). "Colony formation and Annexin V/7AAD staining assays demonstrated that RRM2 silencing could abolish the damaging effects of IKBKE on renal cancer cell growth and apoptosis." (PMID 39664571, 2024). "Notably, altering IKBKE expression did not further influence cell growth or sunitinib sensitivity when RRM2 was knocked down in renal cancer cells, demonstrating that IKBKE primarily modulates cell growth and sunitinib sensitivity through the RRM2-mediated AKT pathway." (PMID 39664571, 2024). "However, it remains unclear whether pharmacological inhibition of IKBKE can affect renal cancer cells." (PMID 39664571, 2024). "CYT387 treatment decreased the expression levels of both IKBKE and RRM2 in renal cancer cells, and 5 μM CYT387 markedly inhibited renal cancer cell growth." (PMID 39664571, 2024). "Subsequently, we constructed stable renal cancer cells with RRM2 knockdown and IKBKE overexpression and found that the effect of IKBKE overexpression on cell proliferation and apoptosis was diminished in shRRM2 cells." (PMID 39664571, 2024). "Collectively, these findings indicate that IKBKE physically interacts with and phosphorylates RRM2 to activate the AKT signaling pathway in renal cancer." (PMID 39664571, 2024). "Consistently, we found that CYT387 treatment resulted in the downregulated expression of both IKBKE and RRM2, and CYT387 effectively inhibited renal cancer cell proliferation and arrested the cell cycle at the G2/M checkpoint." (PMID 39664571, 2024). "As the downregulation of IKBKE can enhance sunitinib sensitivity in renal cancer cells, we evaluated whether CYT387 could promote sunitinib sensitivity in renal cancer cells." (PMID 39664571, 2024). "Importantly, IKBKE knockdown could not further decrease the proliferation of renal cancer cells in the context of RRM2 silencing." (PMID 39664571, 2024). "Importantly, IKBKE knockdown could not further decrease the angiogenesis of renal cancer cells in the context of RRM2 silencing, and RRM2 silencing attenuated the effect of IKBKE overexpression on angiogenesis." (PMID 39664571, 2024).
vasculitis (1 paper, 2020). "In clinical characteristics, we found that IKBKE mRNA expression levels were associated with vasculitis (P = 0.015) and increased C-reactive protein (CRP) (P = 0.021) in SLE patients." (PMID 32146614, 2020). "Furthermore, we found that IKBKE mRNA expression levels were associated with vasculitis in SLE patients (P = 0.015)." (PMID 32146614, 2020). "We noticed that IKBKE mRNA expression levels were significantly lowered (P = 0.015) in SLE patients with vasculitis involved than those without." (PMID 32146614, 2020).